DCDC2B (doublecortin domain containing 2B)
Tractability: No criterion of Open Targets' tractability assessment is met for any kind of drug.
Gene: Protein-coding gene on chromosome 1 (32,209,079 to 32,216,196, forward strand). Ensembl gene ENSG00000222046.
Gene Ontology:
Molecular function: protein binding
Biological process: intracellular signal transduction
Cellular component: microtubule; microtubule organizing center; organelle
Genetic constraint (gnomAD): Loss-of-function variants: 42 observed, 39.28 expected, observed/expected ratio (o/e) 1.07, 90% interval 0.83 to 1.38. The upper end of that interval is the gene's LOEUF score, 1.38, which puts it in group 5 of 6, group 1 being the genes least tolerant of losing a copy. Missense variants: 453 observed, 436.72 expected, observed/expected ratio (o/e) 1.04, 90% interval 0.96 to 1.12. Synonymous variants: 181 observed, 176.89 expected, observed/expected ratio (o/e) 1.02, 90% interval 0.91 to 1.16.
Homologues: Orthologues: chimpanzee DCDC2B (99% identical), macaque DCDC2B (93% identical), pig DCDC2B (79% identical), rabbit DCDC2B (77% identical), dog DCDC2B (75% identical), guinea pig DCDC2B (74% identical), mouse Dcdc2b (60% identical), tropical clawed frog dcdc2b (42% identical). Paralogues in human: DCDC2 (37% identical), DCDC2C (32% identical).
Diseases named in the same sentence as DCDC2B in open-access papers:
DCDC2B is named in the same sentence as 4 diseases in open-access papers, as found by Europe PMC text mining. Sharing a sentence is not in itself a finding about the gene and the disease. The quoted sentences say what the papers report.
deafness (1 paper, 2023). An inherited or acquired condition characterized by the complete loss of the ability to hear from one or both ears. "Another cilia-related transcript is doublecortin-domain containing 2B (DCDC2B, increased 1.9-fold in CAD) which interacts with tubulin 2B (TUBB, increased 1.7-fold in CAD) to affect the hair cell kinocilia, and its mutation likewise leads to recessive deafness." (PMID 37303712, 2023).
Hydrocephalus (1 paper, 2023). Hydrocephalus is an active distension of the ventricular system of the brain resulting from inadequate passage of CSF from its point of production within the cerebral ventricles to its point of absorption into the systemic circulation. "In addition, strong ciliary phenotypes including ventrally curved body axis, hydrocephalus, situs inversus and kidney cysts have been observed in zebrafish following morpholinobased knockdown of dyx1c1 or dcdc2b." (PMID 37237337, 2023).
DCDC2B also shares sentences with these, for which no sentence is quoted: Kidney Cyst (1 paper); situs inversus (1).